CALR (calreticulin)
Diseases named in the same sentence as CALR in open-access papers (continued):
Sharing a sentence is not in itself a finding about the gene and the disease.
tumor (continued). "ROS produced in the process of PDT can cause apoptosis of tumor cells 9, accompanied by the release of damage-associated molecular patterns (DAMPs) including adenosine triphosphate (ATP) or calreticulin (CRT), and high mobility group box 1 (HMGB1) from dying tumor cells 10-13." (PMID 36276646, 2022). "In contrast to the JAK2V617F mutation, which is a single amino acid change, mutant CALR protein represents a large neoantigen that is expressed on the cell surface, and therefore is an attractive target for tumour‐specific immunotherapy in patients with mutCALR‐driven MPN." (PMID 34618358, 2022). "ICD-induced tumor cells release damage-associated molecular patterns (DAMPs) as danger signals, including calreticulin (CALR), high mobility group protein 1 (HMGB1), heat shock proteins (HSPs), and adenosine-5’-triphosphate (ATP), to activate the immune system and enhance antitumor immune responses." (PMID 36189310, 2022). "For example, doxorubicin and cyclophosphamide are capable of causing the translocation of calreticulin, an endoplasmic reticulum chaperone, to the tumor cell surface, thus offering a signal for phagocytosis by dendritic cells and as a consequence, tumor antigen uptake and presentation." (PMID 35844592, 2022). "CALR mutations may inhibit the anti‐tumor effect of ICB by inhibiting the phagocytic function of dendritic cells." (PMID 35355427, 2022). "In BLCA, BRCA and KIRC, higher expression of CALR was associated with more advanced tumor which could be used as an indication of rapid tumor progression." (PMID 34910788, 2021). "Interestingly, in RT-treated patients with NSCLC, tumoral calreticulin levels were positively correlated with tumor levels of phagocytosis-associated genes." (PMID 33920544, 2021). "Moreover, the increase of CALR is more likely to cause tumor metastasis, and the mechanism can be explained by that as a major calcium homeostasis regulator, CALR participates in tumor metastasis through regulating Ca2+ signal to induce cell migration." (PMID 34910788, 2021). "LIC internalized into CT26 cells generates reactive oxygen species (ROS) under laser irradiation to cause immunogenic tumor cell death, during which immunostimulatory signals such as calreticulin are released to further induce T lymphocyte‐mediated tumor cell killing." (PMID 34021727, 2021). "In order to determine whether CALR is associated with tumor progression, we further evaluated the relationship between the CALR and tumor pathological stages based on the GEPIA." (PMID 34910788, 2021). "Due to the stress response after the irradiation of the tumor cells, the damaged and dying cells release damage-associated molecular patterns (DAMPs) including heat shock protein 70 (Hsp70), calreticulin, adenosine-5′-triphosphate (ATP), and high mobility group protein B1 (HMGB1)." (PMID 34768644, 2021). "Immunogenic cell death induces tumor-associated antigen release and translocation of calreticulin to the tumor cell membrane, which acts as an “eat me” signal to DCs, ultimately activating intratumoral DCs that upregulate the costimulatory molecules CD86 and CD70." (PMID 32355277, 2020). "Calreticulin serves as an “eat me” signal, ATP recruits dendritic cells to the tumor sites to cause their maturation to antigen-presenting cells, and HMGB1 facilitates the Toll-like receptor 4 dependent cross-presentation of the released tumor antigens to cytotoxic T-cells." (PMID 32781554, 2020). "In addition to the release of tumor-associated antigens, radiation also provokes the release of calreticulin and ATP, leading to the recruitment and activation of dendritic cells." (PMID 32781554, 2020). "Moreover, sorted memory T cells from HDs are specific to mutant CALR antigens, which suggests that the immune system in HDs has cleared CALR exon 9 mutant cells, providing evidence of tumor immune surveillance against these mutations." (PMID 33086698, 2020).
tumor (continued). "Interestingly, both oxaliplatin and cisplatin induced the release of HMGB1, but it was only oxaliplatin that caused calreticulin translocation and effectively contributed towards tumor immunogenicity." (PMID 32781554, 2020). "Therefore, the expression of calreticulin after RT implies susceptibility of tumor cells to T cell killing and can be used as a biomarker for the response to immunotherapy and RT." (PMID 30115069, 2018). "As a consequence of ICD, damage-associated molecular patterns (DAMPs), such as ATP, uric acid and high mobility group protein Box1 (HMGB1), from tumor cells and by the translocation of calreticulin, an ER- associated chaperone, to the tumor cell surface are released and amplify immune response." (PMID 30352078, 2018). "Interestingly, this correlation analysis showed that mainly in the ICD clinical settings tumoural CALR levels positively correlated with the tumoural levels of phagocytosis-associated genes (especially PLA2G5, PLD1, RAB5A, VAMP7, STAB2)." (PMID 26314964, 2015). "In this case, the magnitude of the anti-tumor effect appeared comparable to that recently described in mice vaccinated with vaccinia virus-based vectors expressing E7 fused with calreticulin, i.e., a protein strongly favoring Class I association of antigenic peptides." (PMID 25760140, 2015). "Augmented CTL lysis specific for several tumor-associated antigens was largely dictated by the presence of calreticulin on the surface of tumor cells and constituted an adaptive response to endoplasmic reticulum stress, mediated by activation of the unfolded protein response." (PMID 24480782, 2014). "Thus, we examined the effects of radiation on molecules that have been implicated in enhancing CTL-mediated tumor lysis, including calreticulin and APM components." (PMID 24480782, 2014). "In particular, a multifaceted response to tumor antigens released following necrosis and apoptosis results from exposure to PAMPs, danger associated molecular patterns (DAMPs: such as heat shock proteins, uric acid, calreticulin, HMGB-1), and cytokines (such as IFN 1, interleukin 12, and TNF α)." (PMID 30514385, 2018). "Recent study has shown that loss of ER chaperone calreticulin results in the prevention of phagocytosis and antigen presentation in dendritic cells, and translocation of calreticulin to the plasma membrane induced by anti-neoplastic drugs anthracycline triggers tumor immunogenicity." (PMID 25941664, 2015). "The suppression of PTP1B, by either geneticknockdown or pharmacological inhibition, enhanced the immunogenicityof tumor cells by increasing surface-exposed calreticulin and phagocytosisof cancer cells." (PMID 41432362, 2026). "The expression of the chaperone of the endoplasmic reticulum (ER), calreticulin, on the cell membrane of dying tumor cells is particularly indicative of this." (PMID 40002275, 2025). "Meanwhile, calreticulin translocates to the outer membrane of tumor cells, and functions as an "eat me' signal and facilitates APC phagocytosis of tumor associated antigens (TAAs)." (PMID 40521175, 2025). "The findings showed that tumor tissues had much lower levels of CALR expression than nearby tissues." (PMID 39812156, 2025). "ABab-I mice mount robust CD8+ T cell responses in vivo against viral (Cytomegalovirus (CMV), Human Papillomavirus (HPV)), tumor-associated antigens (MAGE-A12), and tumor-specific neoantigens (mutant KRAS and CALR)." (PMID 40593800, 2025). "During ICD, dying tumor cells release specific molecules known as damage-associated molecular patterns (DAMPs), including high mobility group protein B1 (HMGB1), ATP, and calreticulin (CRT), among others, into the surrounding environment." (PMID 40777132, 2025). "Calreticulin (CRT), a damage-associated molecular pattern (DAMP) molecule, is released and translocated from the endoplasmic reticulum to the tumor cell membrane during ICD." (PMID 40978046, 2025).
tumor (continued). "This form activates antitumor immune responses by promoting the exposure and release of damage‐associated molecular patterns (DAMPs), such as calreticulin, ATP, and HMGB1, which stimulate dendritic cell maturation and tumor‐specific T lymphocyte responses." (PMID 40916083, 2025). "Next, we measured expression of immunogenic proteins such as HMGB1, HSP70 and calreticulin in 1200V-treated apoptotic tumor cells by flow cytometry and demonstrated that they were all upregulated when compared to untreated or 600V-treated cells." (PMID 41194931, 2025). "Cytotoxic therapies are known to induce the upregulation of “eat-me” signals like calreticulin on tumor cells, which can trigger phagocytosis." (PMID 40078999, 2025). "THT reduced tumor burden through cell death mechanisms, including upregulated ICD marked by calreticulin exposure within 48 h; however, tumor regrowth was observed within 6 days post‐treatment." (PMID 40458962, 2025). "It induced immunogenic cell death (ICD) characterized by calreticulin exposure and ATP release, while modulating the tumor microenvironment by downregulating MMP-3, MMP-9, VEGF, and vimentin, and restoring epithelial markers." (PMID 41304785, 2025). "ICD promotes the exposure of calreticulin to the surface of tumor cells through endoplasmic reticulum stress characterized by reactive oxygen species accumulation, and promotes the release of HMGB1 and other DAMPs (including ATP)." (PMID 41425703, 2025). "Then, using flow cytometry, we assessed the expression of immunogenic cell death (Fas, calreticulin) and cellular stress (PD-L1, Rae-1γ) markers by tumor cells in tumor single cell suspensions." (PMID 40280970, 2025). "For example, calreticulin interacts with a variety of immune cell receptors such as CD91 that can stimulate phagocytosis of immune cells against tumor cells, while HMGB1 release can play an important role in the activation of antigen-presenting cells." (PMID 40356923, 2025). "Upon lysis, tumor cells infected with rNDV release substantial quantities of DAMPs, such as calreticulin (CRT), ATP, and high-mobility group box 1 (HMGB1)." (PMID 41479917, 2025). "qRT-PCR was used to assess mRNA expression levels of CALR in tumor versus normal cells, while Western blotting confirmed protein expression." (PMID 40978026, 2025). "Chronic cisplatin exposure, especially in resistant tumor models, further amplifies cGAS/STING activation, increasing PD-L1, MHC class I, and calreticulin levels, making tumor cells more recognizable to immune cells." (PMID 39949780, 2025). "Simultaneously, RT upregulates FAS (death receptor), MHC class I, translocation of calreticulin to tumor cell surfaces, and increases the release of HMGB1 from dying tumor cells." (PMID 40141437, 2025). "Given the reported regulatory effects of CALR on cadherin angiogenesis, our findings suggest a possible CALR–cadherin axis influencing tumor progression in RMS." (PMID 40710368, 2025). "Radiotherapy can increase the expression of CALR on tumor cells, which acts as a pro-phagocytic “eat me” signal for DCs, facilitating their recognition and engulfment of tumor cells." (PMID 40356601, 2025). "In contrast, the expression levels of CALR in the cell lines used in this study were generally higher in the tumor-derived cell lines than in the non-tumor-derived cell lines (right)." (PMID 39744689, 2025). "The types of DAMPs from the damaged tumor cells after RT include calreticulin (CALR), adenosine triphosphate (ATP), type I interferon (IFN), heat shock proteins (HSPs), S100 proteins, and interleukin-1 beta (IL-1β)." (PMID 40895459, 2025). "Tumor cells undergoing ICD release or express ICD‐related damage‐associated molecular patterns (DAMPs), such as calreticulin (CRT), high mobility group box‐1 protein (HMGB1), adenosine triphosphate (ATP), and interferon‐β (IFN‐β)." (PMID 40504080, 2025).
tumor (continued). "Activation of the tumor-specific immune response is accompanied by the cell surface exposure of calreticulin and heat-shock proteins, the secretion of adenosine triphosphate, and the release of high mobility group box-1." (PMID 40207233, 2025). "CALR is expressed in nearly all cells in the TME, IL1R1 is mainly expressed in tumor-associated fibroblasts and endothelial cells, and the expression levels of IFNG and IFNB1 are minimal, primarily by T lymphocytes." (PMID 40928500, 2025). "After treatment, increased calreticulin expression in tumor cells, together with increased lymphoid cell lineages, was observed in non-recurrent cases." (PMID 40483270, 2025). "Ferromagnetic vortex-domain iron oxide nanorings (FVIOs) induce mild thermal stress, leading to the exposure of calreticulin (CRT) on tumor cells." (PMID 40887613, 2025). "In a study comparing photon and proton radiation on various tumour cell lines, proton-irradiated cells showed increased calreticulin cell-surface expression, a protein that enhances tumour cell sensitivity to cytotoxic T-cell killing." (PMID 40308498, 2025). "Radiation also induces the release of danger signals, such as HMGB1, ATP, and translocation of calreticulin to the tumor cell surface." (PMID 39941843, 2025). "Radiotherapy can promote the translocation of calreticulin to the cell membrane and then enhance the phagocytosis of tumor cell by DCs." (PMID 40475019, 2025). "Supporting the activation of immunogenic apoptosis, we observed a significant increase in plasma HMGB1 levels and enhanced exposure of calreticulin on the surface of B16F10 tumor cells (5th column)." (PMID 39681571, 2024). "The tumor microenvironment is complex, and in addition to calreticulin, abnormal expression of the regulatory protein macrophage inhibitory factor (MIF) can also have a great impact on the survival of tumor cells." (PMID 38464520, 2024). "Certain chemotherapeutic agents can lead to immune cell death (ICD) in tumor cells by inducing calreticulin (CRT) exposure." (PMID 39545088, 2024). "Nevertheless, the NKp46 ligand externalized calreticulin (ecto-CRT) was only recently described on tumor cell surface." (PMID 39179536, 2024). "Overexpression of CALR promotes tumor metastasis in CRC cells by regulating calcium ion signaling and cell migration." (PMID 38542474, 2024). "Such a paradox can be explained by the different cellular location and functions of CALR in the normal and tumor settings." (PMID 38245510, 2024). "Treatment with hydrogel/CN-Pt/GEM + NIR, which included hydrogel/CN-Pt + NIR and hydrogel/Ge, elicited calreticulin (CRT) exposure in tumor cells when compared to that in the control, hydrogel, and hydrogel/CN-Pt groups." (PMID 38902678, 2024). "Meanwhile, we observed an increased secretion of high-mobility group protein 1 (HMGB1) in the culture supernatant and expression of calreticulin (CRT) on the tumor cell surface after treatment with E/S Lip and P-E/S Lip." (PMID 39068444, 2024). "Our findings suggest that the STK10 inhibitor SB633825, in collaboration with bortezomib, enhances CALR exposure, thereby demonstrating a more robust anti-tumor immune activation." (PMID 39555062, 2024). "Intriguingly, in vivo studies have demonstrated that subcutaneous peritumoral inoculation of recombinant T. cruzi calreticulin (rTcCalr) promotes local T cell infiltration and delays tumor development." (PMID 39125875, 2024). "Calreticulin, a chaperone protein residing in the endoplasmic reticulum of eukaryotic cells, has been proposed to exhibit antiangiogenic and tumor growth regression properties." (PMID 39125875, 2024). "Research has found that the recognition and uptake of apoptotic tumor cells by DCs depend on the binding of calreticulin on the apoptotic tumor cell surface to its receptor LRP1, which can activate tumor-specific CD8+ T cells." (PMID 38835772, 2024).
tumor (continued). "In a 2023 study, a self-amplified biomimetic nanosystem, mEHGZ, was constructed by encapsulation of epirubicin (EPI), glucose oxidase (Gox) and hemin in ZIF-8 nanoparticles and coating them with calreticulin (CRT) over-expressed tumor cell membrane." (PMID 39136021, 2024). "One such strategy involves tumor-derived stanniocalcin-1 (STC1) interacting with calreticulin (CRT), one of the best identified damage-associated molecular patterns (DAMPS), which takes part in dead tumor cell removal because it can act as a “receptor”." (PMID 38927447, 2024). "In tumor immunology, DCs are often activated by “danger signals” such as Damage-Associated Molecular Patterns (DAMPs), including ATP, HMGB1, Calreticulin (CRT), and the S100 protein family." (PMID 38545114, 2024). "It is also known that adequate radiotherapy can enhance anti-tumor immune responses through immunogenic cell death (ICD) via the release of damage-associated molecular patterns and exposure of MHC Class I and calreticulin." (PMID 38330507, 2024). "CALR dysregulation is also linked to its interaction with TGF-β signaling pathways, influencing immune suppression and tumor progression." (PMID 39469643, 2024). "This reveals the crucial role of the calreticulin-LRP pathway in promoting phagocyte uptake of apoptotic tumor cells and in the process of antigen cross-presentation." (PMID 38835772, 2024). "Mechanistically, DHA restored the immunogenicity of CDDP-induced dying tumor cells by activating the PERK/eIF2α pathway to induce CALR exposure." (PMID 39090653, 2024). "This reaction enabled the generation of a large amount of ROS in the tumor environment to enhance the PDT to improve the ICD by generating calreticulin (CRT), adenosine triphosphate, and high mobility group protein B1 (HMGB1)." (PMID 40808797, 2024). "In ccRCC (RENCA) animal models, researchers observed a highly remarkable tumor volume reduction and an increase in calreticulin, perforin, and NKp46 staining." (PMID 38443363, 2024). "Helminths and protozoan parasites, as well as their derivatives such as Echinococcus granulosus protein KI-1, Toxoplasma gondii GRA15II, and Trypanosoma cruzi calreticulin, have demonstrated the ability to inhibit tumor growth, angiogenesis, and metastasis." (PMID 39367471, 2024). "Our study also highlights the importance of the PERK-mediated eIF2a phosphorylation-induced CALR exposure for anticancer immunosurveillance and enhanced anti-tumor effect of C + D treatment." (PMID 39090653, 2024). "CALR has been identified as a primary pro-phagocytic signal on the surface of various human cancers, promoting the recognition and engulfment of tumor cells by phagocytes." (PMID 39682299, 2024). "Given their roles in calcium ion homeostasis, the influence of TMCO1 and CALR on the tumor immune microenvironment deserves deeper examination." (PMID 39479348, 2024). "Calreticulin facilitates tumor cell uptake by DCs and boosts chemotherapy-induced anti-tumor responses by reducing tumor growth after treatment." (PMID 39456655, 2024). "Exposed calreticulin represents an “eat me” signal for dendritic cells and macrophages, which leads to natural killer cell and neutrophil recruitment to the tumor site." (PMID 36831435, 2023). "One of these DAMPs, called calreticulin, is exposed after EP, promoting the subsequent tumor infiltration by granzyme B-cells, However, its release was not enhanced only via exposure to a chemotherapeutic drug." (PMID 37999139, 2023). "We discovered immunogenic cell death (ICD) in a portion of cells induced by the cavitation effect from LIFU-TMD, characterized by the increased expression of calreticulin (CRT) on the tumor cell surface." (PMID 37139047, 2023).